ATG4AP1 (autophagy related 4A cysteine peptidase pseudogene 1)
Gene: Processed pseudogene on chromosome X (82,998,699 to 82,999,236, forward strand). Ensembl gene ENSG00000232735.
Diseases named in the same sentence as ATG4AP1 in open-access papers:
ATG4AP1 is named in the same sentence as 1 disease in open-access papers, as found by Europe PMC text mining. Sharing a sentence is not in itself a finding about the gene and the disease.
ATG4AP1 shares sentences with these, for which no sentence is quoted: breast tumors (1 paper).